LGR5 (leucine rich repeat containing G protein-coupled receptor 5)
Diseases named in the same sentence as LGR5 in open-access papers (continued):
Sharing a sentence is not in itself a finding about the gene and the disease.
adenoma (continued). "In this study, we aimed to evaluate the immunohistochemical expression of stem cell marker LGR5 and its co-expression with Β-catenin in sporadic colorectal carcinoma versus adenomas and to assess the correlation of their expression with the clinicopathological characters." (PMID 37512045, 2023). "Furthermore, the growth of adenoma organoids from Lgr5–creER,Apcflox/flox mice was enhanced by metformin, a complex I inhibitor, confirming that the pharmacological inhibition of complex I can also enhance colon adenoma organoid growth." (PMID 36187114, 2022). "APC deletion in LGR5+ colonic crypt base SCs induce the rapid transformation into adenomas: Aberrant WNT activity in the LGR5+ SC compartment might be responsible for the tumor-initiating process." (PMID 33562604, 2021). "Hence, loss of Apc in Krt15+ cells—a heterogeneous population, encompassing Lgr5+ and Lgr5− cells, spanning the crypt base as well as the TA zone—leads to adenomas that occasionally progress to invasive adenocarcinomas." (PMID 33673710, 2021). "Furthermore, in lineage tracing studies, Schepers and colleagues showed that these adenomas maintain Lgr5+ stem cell activity." (PMID 34071313, 2021). "Indeed, targeted deletion of Apc in Lgr5+ ISCs drives aberrant Wnt signalling and hyperproliferation, leading to rapid adenoma formation in mice." (PMID 33673710, 2021). "LGR5 has been reported to have high expression in most of the CRC cell lines and adenomas but this overexpression has nothing to do with progression of tumor as presence of LGR5 increases cell-cell adhesion which in turn promotes stemness and hampers invasiveness and migration." (PMID 33489917, 2020). "Furthermore, the series of studies have suggested that enhancement of Lgr5 expression is correlated with an evolution from adenoma to adenocarcinoma." (PMID 32671503, 2020). "Thus, loss of Pygo or Bcl9 promotes secretory cell metaplasia, apparently at the expense of stem cell-like fates, given the downregulation of Lgr5 and stem cell signature genes in these adenomas." (PMID 30760710, 2019). "Repression of LGR5 further increases the sensitivity of adenoma cells to EGFR inhibition." (PMID 29149105, 2018). "Furthermore, LGR5 silencing in adenoma cells enhances the proliferative state of EGF-treated adenoma cells, as observed by induction of Ki67 expression, enhanced cell cycle progression and reduced survival." (PMID 29149105, 2018). "Supporting a role for Jag1 in adenoma formation and by extension in tumor-initiating cell (TIC) activity, Jag1 KO adenomas expressed reduced levels of Lgr5, Bmi1, Ephb2, c-Myc, Sox9, and Cd133 compared to the Jag1 WT, as determined by qRT-PCR and in situ hybridization (ISH)." (PMID 30065304, 2018). "Interestingly, any requirement for a reduction in LGR5 expression during the adenoma-carcinoma transition fits with the LGR5 protein expression pattern we have observed from our panel of human CRC cell lines." (PMID 29844449, 2018). "LGR5 expression was still higher in colon carcinomas than in adenomas." (PMID 29652830, 2018). "Given the enhanced proliferative response to EGF with LGR5 silencing, we next investigated whether this could sensitise adenoma cells to EGFRi." (PMID 29149105, 2018). "For this we utilised the RG/C2 adenoma cell line (KRASwt) which harbours high levels of LGR5." (PMID 29149105, 2018). "Nether-the-less, these results build on our previous identification of LGR5 as a pro-survival factor in PGE2-treated adenoma cells and indicate that lowering of LGR5 expression could be an important event for adenoma-carcinoma progression." (PMID 29149105, 2018). "Indeed, the majority of adenoma cell lines contain high LGR5 expression, while most carcinoma cell lines exhibit low or absent LGR5 (except for metastatic cell lines))." (PMID 29149105, 2018). "Furthermore, observations of LGR5 expression suggest that a stem cell/progenitor cell hierarchy is maintained in early stem-cell-derived adenomas." (PMID 29652830, 2018).
adenoma (continued). "With respect to the relationship between stem-like cells (labeled with LGR 5 and ALDH1) and clinicopathological parameters of patients with adenomas and CRCs, we have observed slight increased scores of LGR5 and ALDH1 positive cells in the adenomatous epithelium with high degree of dysplasia." (PMID 28484082, 2017). "In addition, it is present near the Lgr5 positive stem cells in the normal gut and in the intestinal ApcMin/+ adenomas." (PMID 28086833, 2017). "In an alternate murine intestinal tumor model, differentiated colon epithelial cells with LGR5−/KRASwt status demonstrated the potential to dedifferentiate into LGR5+ adenoma-initiating cells when KRASmut and transcription factor NF-κB were activated to enforce high Wnt signaling." (PMID 26744320, 2016). "We corroborated this in vitro observation by treating adenoma bearing Lgr5-CreER." (PMID 26956214, 2016). "Notably, the expression levels of LGR5 in adenoma samples were significantly higher than those in normal mucosae, suggesting that adenoma cells were successfully separated from normal cells." (PMID 27589228, 2016). "Additionally, murine adenomas revealed continual LGR5+ stem cell activity, providing functional evidence of a cancerous stem cell population in primary intestinal adenomas." (PMID 25751518, 2015). "Moreover, ectopic crypts found in traditional serrated adenomas show basal LGR5 mRNA, indicating that they replicate the stem cell organization of normal crypts with the development of a cellular hierarchy." (PMID 25728748, 2015). "Thus, applying this insight to conventional adenomas, the large number of LGR5+ cells suggests a large pool of cells with stem cell potential, but not necessarily a large number of functioning stem cells." (PMID 25728748, 2015). "Conditional deletion of APC exclusively in the LGR5+ ISCs of a murine model led to the rapid growth and spread of large adenomas in the small intestine and colon, whereas deletion of Apc in the non-stem cell compartment, resulted in the growth inhibition of adenomas." (PMID 24789370, 2014). "Additionally, Lgr5+ cells were found to be the multipotent stem cells that produced all other adenoma cell types in intestinal adenomas." (PMID 24340024, 2013). "Apc-mutant Lgr5+ cells were reported to be the origin of progressively growing adenomas." (PMID 24340024, 2013). "In fact, the level of Lgr5 expression in adenomas of 2 intestinal tumorigenesis mouse models, Apc1322T (1322T) and ApcR850X (Min), differed: 1322T tumors had higher Lgr5 expression levels than Min tumors, and more than half of the epithelial portion of the adenomas showed Lgr5 expression." (PMID 24340024, 2013). "Moreover, LGR5 expression was higher in adenomas with intestinal-type glands than in those with gastric-type glands (p = 0.024)." (PMID 24340024, 2013). "In most of the low-grade adenomas, at least 5% of the tumor cells were LGR5+ cells." (PMID 24340024, 2013). "In addition, recent reports have highlighted the heterogeneous expression of the Wnt target and stem cell marker LGR5 in both adenomas and carcinomas." (PMID 24144042, 2013). "Lgr5 stem cells are also tumorigenic, mice with deletion of APC gene, an essential Wnt signaling gene resulted β-catenin upregulation at the base of pyloric glands, and within 2–3 weeks, these Lgr5 cells can grow into highly proliferative, β-catenin-positive adenomas." (PMID 23217022, 2012). "Moreover, EGF suppresses the expression of LGR5 (a co-receptor for Wnt/β-catenin signaling and marker of both normal intestinal stem cells and cancer stem cells) finely regulated during the adenoma-carcinoma progression, the development and maintenance of CRC-derived metastasis." (PMID 37853459, 2023). "Interestingly, deletion of Jag1—but not the canonical Notch effector Rbpj—in APC-deficient Lgr5+ cells disrupted the Paneth-cell tumour niche and compromised adenoma growth, suggesting non-canonical Notch signalling as a prospective therapeutic target." (PMID 33673710, 2021).
adenoma (continued). "Thus, it is possible that suppression of LGR5 may suppress the stem potential of adenoma cells and may prevent adenoma formation." (PMID 33785874, 2021). "Because LGR5 is a target of Wnt/β-catenin signaling that occurs during the adenoma–carcinoma sequence in CRC, LGR5 expression in MMR-P cases, which may involve the adenoma–carcinoma sequence, may be higher than that in MMR-D cases, which may involve the serrated neoplasia pathway." (PMID 32293346, 2020). "Counting results showed that the grading scores of cells positive for LGR5 and ALDH1 in the adenoma/CRC epithelium were significantly increased relative with the control epithelium, and associated with the degree of dysplasia in the adenoma and node involvement in the CRC (all P < 0.05)." (PMID 28484082, 2017). "Furthermore, intestinal stem cells, marked by the Wnt target gene Lgr5 were identified as the cell of origin for intestinal cancer, as truncation of Apc specifically in Lgr5+ cells resulted in widespread, rapid, development of adenoma’s throughout the small intestine and colon." (PMID 27196929, 2016). "However, the question remains whether the Lgr5+ cells that are distributed diffusely across the adenoma and co-express ISC markers also have stem cell features; they seem too numerous to be stem cells and lack the spatial restriction to the base of the glands." (PMID 24340024, 2013). "al, 2021 reported that tubular adenomas are enriched in cells referred to as ASC (Adenoma-Specific Cells) and expressed OLFM4 and LGR5." (PMID 41282138, 2025). "The relation of LGR5 expression to the histopathological types of specimens was statistically significant (p = 0.048) because of more intense LGR5 immunoreactivity in CRC and adenoma than in normal mucosa." (PMID 37512045, 2023). "Especially, we identified the dysregulated stem genes including LGR5, c-Myc, and OLFM4 as the markers of adenoma, which are well preserved in HRCA-PDOs." (PMID 37667332, 2023). "We have previously used a various set of cell markers, such as Musashi, CD133, LGR5 and ALDH1, as biomarkers to examine the presentation of SCs in different compartments of adenomas." (PMID 36466926, 2022). "While loss of Apc in Lgr5+ cells leads to tumorigenesis, we found that the growth and number of adenomas was more robust in the Dclk1+/DSS model due to the mosaic pattern and low levels of expression in the colon of Lgr5-CreERT2 mice." (PMID 36860494, 2022). "Because LGR5 is a ‘Wnt amplifier’55,56 expansion of LGR5+ cells may be a key step in allowing cells without permissive mutations in other pro-oncogenic signalling pathways to expand, driving the formation of adenomas." (PMID 33785874, 2021). "Ascl2, which is a master regulator of cellular stemness in Lgr5+ cells, is dramatically overexpressed during spontaneous colon tumorigenesis in Apc+/Min-FCCC mice and in humans (>7-fold in adenomas; >10-fold in carcinomas)." (PMID 33671373, 2021). "Immunofluorescence analysis confirmed a corresponding decrease in the Lgr5-GFP+ tumor cell area and Sox9+, Prox1+, and Cd24+ adenoma cells in the intestinal sections 18 days after Lef1 deletion." (PMID 34788095, 2021). "Because LGR5 and ALDH1 are the two most promising and established stem-like markers in adenoma/CRC, we examined the immunoreactivity of LGR5 and ALDH1 in the adenoma/CRC epithelium with semi-quantitative analysis." (PMID 28484082, 2017). "Then, the grading scores of LGR5 positive and ALDH1 positive cells in the adenomatous/cancerous epithelium were analyzed against clinical pathological parameters in adenomas and CRCs." (PMID 28484082, 2017). "The presence of stem-like markers in different stages of the adenoma-carcinoma sequence was evaluated with IHC using Msi, CD133, LGR5 and ALDH1 antibodies." (PMID 28484082, 2017). "Lineage tracing studies have shown that murine adenomas can originate from crypt base SC origin, since targeted APC deletion in murine LGR5+ intestinal SC gave rise to adenomas." (PMID 26744320, 2016).
adenoma (continued). "To determine if the expression of the stem cell marker LGR5 is altered during human adenoma progression, we carried out chromogenic ISH on a panel of human FFPE hyperplastic polyps, adenomas and adenocarcinomas of all stages (n = 66)." (PMID 25728748, 2015). "Immunohistochemical analysis of β-catenin expression in the small intestine of both Lgr5-GFP-CreERT2+Apcfl/fl and Lgr5-GFP-CreERT2+Apcfl/flBrgfl/fl mice revealed a mixture of micro and macro-adenomas with nuclear β-catenin at a range of time points." (PMID 25010414, 2014). "To this aim we studied the expression of LGR-5, MSI-1, DCAMKL-1, CD133 and ALDH1-A1 in normal mucosa, in MDF (microscopic precancerous lesions) and in macroscopic tumours (adenomas) of DMH-induced rats using immunohistochemistry." (PMID 23374535, 2013). "Another key difference in our study is unlike Apcmin/+ mice and Lgr5-CreERApcfl/fl mice that develop adenomas chiefly in the small intestine, lesions in our mouse models arise in the colon and cecum, which more closely reflects human CRC." (PMID 40179020, 2025). "Of note, although cells expressing the PC marker lysozyme (LYZ1) were notable in Lgr5-derived tumors (Lgr5/Apc: 30.0% ± 18.5% positive tumor cells), they were almost absent in adenomas that originated from PCs (Lyz1/Apc: 0.48% ± 1.16%)." (PMID 38902475, 2024). "Interestingly, we noticed that when compared to normal mucosa, both primary adenoma and CA organoids demonstrated significantly higher expression of several colon stem cell signature genes including OLFM4, LGR5, c-Myc, and CD166." (PMID 37667332, 2023). "Cre-mediated recombination in a second mouse strain, R26-tdTomato ApccKO/cKO Lgr5-EGFP-CreERT2, resulted in the knockout of the Apc gene in IESCs, accompanied by the production of the red fluorescent protein tdTomato in growing adenomas (right part of the diagram)." (PMID 36077674, 2022). "Supporting our results in mouse adenomas, the analysis of human tumours at different stages revealed that Thbs1 is highly expressed in Lgr5+ cells only in early-stage adenomas but not in advanced carcinomas." (PMID 35543624, 2022). "In particular, the ectopic crypts of traditional serrated adenomas harbour basal LGR5+ cells, potentially linking the disruption of BMP gradients to the de novo generation of an ectopic niche and/or the migration of LGR5+ cells to a permissive site in response to chemotactic TME signals." (PMID 33673710, 2021). "Whereas Hes1 deletion in normal Lgr5+ or Bmi1+ ISCs compromised self-renewal without impacting homeostasis, deletion of Hes1 in the Lgr5+ or Dclk1+ CSCs of ApcMin/+ adenomas elicited apoptosis, alleviating tumour burden." (PMID 33673710, 2021). "LGR5-expression patterns differ between human non-serrated conventional adenomas and serrated lesions (sessile serrated adenomas/polyps and traditional serrated adenomas), likely reflecting differences in their histogenesis and their niche/TME." (PMID 33673710, 2021). "High LGR5 protein expression was present in all adenoma cell lines (AA/C1, AN/C1, BH/C1, RG/C2) but absent or low in the majority of carcinoma cell lines (DLD-1, HCA7, HCT116, HCT-15, HT29, LS174T, RKO)." (PMID 29844449, 2018). "LGR5 has an important role in the EGF-mediated survival and proliferation of early adenoma cells and could have clinical utility in predicting response of CRC patients to EGFR therapy." (PMID 29149105, 2018). "LGR5+ cells are known to exist outside the stem cell niche during CRC progression, and the requirement for epidermal growth factor (EGF) signalling within early adenomas remains to be fully elucidated." (PMID 29149105, 2018). "In line with the effect of Ap4 deletion in adenomas, GSEA indicated that mRNAs characteristic for Lgr5-positive ISCs and several factors involved in Wnt/β-catenin and Notch signaling pathways were preferentially downregulated upon deletion of Ap4: for example Sox4, Axin2, EphB3 were downregulated." (PMID 30177706, 2018).
adenoma (continued). "However, counting results showed that the densities of cells positive for stem-like markers LGR5 and ALDH1 in CRC tumor stroma were slightly higher than that in adenomas." (PMID 28484082, 2017). "Notably, in those sections with transitional crypts (6 of 30 adenoma sections, 5 of 30 CRC sections), a changed presentation pattern of cells positive for stem–like markers (Msi, CD133, LGR5 and ALDH1) was observed." (PMID 28484082, 2017). "In the adenoma stroma, the grading scores of LGR5 positive and ALDH1 positive cells were not correlated with degree of dysplasia or histological types (data not shown)." (PMID 28484082, 2017). "LGR5 is known to be a stem cell marker in the murine small intestine and colon, however the localization of LGR5 in human adenoma samples has not been examined in detail, and previous studies have been limited by the lack of specific antibodies." (PMID 25728748, 2015). "Within the majority of lesions we observed little uniformity of LGR5 expression along the gland length and considerable variability in expression across the adenoma, though still with no apparent conservation of normal stem cell architecture." (PMID 25728748, 2015). "We provided evidence of adenomatous glands that expressed LGR5 only on one side or branch, a feature that implied during conventional adenoma progression LGR5-positive cells are no longer confined to the crypt base." (PMID 25728748, 2015). "We found that SSA/Ps (n = 7) displayed expansion of the LGR5-expressing compartment, although unlike conventional adenomas we saw that LGR5 in SSA/Ps remained generally localized to cells in the base of the crypt." (PMID 25728748, 2015). "LGR5 expression in the upper and lower halves of the gland differed little in the adenoma, unlike that in IM and GAs with basal LGR5 expression." (PMID 24340024, 2013). "Introducing adenomatous polyposis coli mutations reportedly lead to adenoma only in LGR5+ (leucine-rich repeat containing G protein-coupled receptor 5) stem cells, which resembles ISC, but not in LGR5− cell population, marking LGR5 a cancer stem cell marker in CRC." (PMID 37950151, 2023). "Importantly, the knockdown of LGR5 increases the sensitivity of adenoma cells to the EGFR inhibitor gefitinib, suggesting low LGR5 expression could be used clinically to predict patients who may benefit from EGFR therapies." (PMID 29149105, 2018). "In summary, this study applied ISH to a panel of human FFPE normal colon, adenoma and carcinoma samples (n = 66) to show that conventional adenomas display extensive expression of the stem cell marker LGR5, and this expression is no longer restricted to the base of adenomatous crypts." (PMID 25728748, 2015). "However, a detailed analysis of the LGR5 stem cell architecture in the serrated pathway of colorectal tumorigenesis, and how it may differ from the classical adenoma/carcinoma progression has not been reported." (PMID 25728748, 2015). "Since in FAP patients, non-steroidal anti-inflammatory drugs cause adenomas to regress, it is tempting to suggest that this effect could be mediated through the lowering of PGE2 levels, which in turn reduce LGR5 expression and the survival of LGR5+ adenoma stem cells." (PMID 29652830, 2018).